EPHB4 (EPH receptor B4)
Diseases named in the same sentence as EPHB4 in open-access papers (continued):
Sharing a sentence is not in itself a finding about the gene and the disease.
prostate carcinoma (22 papers, 2005 to 2026). A carcinoma that arises from epithelial cells of the prostate gland. "Loss of EphB4 prevented the development of prostate cancer, and the results were replicated with sEphB4-alb." (PMID 40044981, 2025). "EPHB4 is overexpressed in the majority of prostate cancers, particularly in advanced disease and is associated with a poor outcome." (PMID 31641103, 2019). "EphB4 is overexpressed in 66% of prostate cancer clinical samples and has been implicated in prostate cancer development and progression." (PMID 25886373, 2015). "It has been shown using targeted siRNA sequences that knockdown of EphB4 in prostate cancer causes a significant reduction in cell motility in vitro and tumor growth in vivo." (PMID 25886373, 2015). "We employed transient knockdown of EPHB4 in prostate cancer cells, coupled with gene microarray analysis, to identify genes that were regulated by EPHB4 and may represent linked tumor-promoting factors." (PMID 25886373, 2015). "We have thus observed that induction of EphB4 is required for the initiation of prostate cancer in PTEN null mouse and that signaling downstream from EphB4 is required in androgen deprivation and thus castration resistant prostate cancer." (PMID 40044981, 2025). "PTEN deletion induces EphB4 and ephrin-B2 in prostate cancer which was substantially reduced when EPHB4 is deleted in the same prostate epithelial cells." (PMID 40044981, 2025). "To test the contribution of EphB4 downstream from PTEN null prostate cancer, we developed conditional knock out of EphB4 and crossed with conditional PTEN null mice." (PMID 40044981, 2025). "We and others have described elevated levels of EphB4 in prostate cancer and shown that EphB4 is induced in prostate cancer by both the PI3K pathway and the β-catenin pathway." (PMID 40044981, 2025). "Targeting EphB4 should be tested in prostate cancer especially those resistant to androgen deprivation therapy." (PMID 40044981, 2025). "This was achieved by deleting EPHB4 in prostate epithelium in the context of PTEN knock out prostate cancer mouse model." (PMID 40044981, 2025). "The overexpression of EphB4 in 22Rv1 prostate cancer and MCG-10A mammary epithelial cell lines led to an initial increase in migration, invasion and anchorage-independent growth, crucial phenotypes necessary for metastasis formation." (PMID 35163601, 2022). "Conversely, EphB3 and EphB4 were upregulated in prostate cancer cells, possibly contributing to invasion and metastasis through the deregulation of contact inhibition of locomotion (CIL) as CIL was restored upon knockdown of the two receptors." (PMID 33430066, 2021). "For example, for metastatic prostate cancer cells, it has been shown that they invade fibroblasts dependent on EphB3 and EphB4 signaling and activation of Cdc42." (PMID 34502237, 2021). "Inhibition of EphB4 promoted tumor cell growth which was mediated by the activation of ER stress in prostate cancer." (PMID 32733636, 2020). "Previous report revealed that EphB4 inhibition induced prostate cancer cell death via activation of ER stress." (PMID 32733636, 2020). "EPHB4 knockdown in human (PC-3, 22Rv1 and LNCaP) and mouse (Myc-CaP & Myc-CaP; Pten KO) prostate cancer cell lines resulted in a decrease in cell viability measured after 72 h." (PMID 31641103, 2019). "Together, our study indicates a role for EPHB4 inhibition in the induction of immunogenic cell death with implication for prostate cancer therapy." (PMID 31641103, 2019).
prostate carcinoma (continued). "We examined EPHB4 mRNA expression in published human prostate cancer expression datasets and observed higher EPHB4 expression in metastatic castration-resistant prostate cancer (mCRPC) as compared to the corresponding normal or primary tumor tissues." (PMID 31641103, 2019). "Here, we show that high expression of EPHB4 correlated with poor survival in prostate cancer patients and EPHB4 inhibition induced cell death in both hormone sensitive and castration-resistant prostate cancer cells." (PMID 31641103, 2019). "In summary, our study has identified a novel role for the receptor tyrosine kinase EPHB4 signaling pathway in regulating prostate cancer cell survival that can be exploited for targeted therapy." (PMID 31641103, 2019). "To determine the functional significance of EPHB4 overexpression in prostate cancer, we knocked down EPHB4 with specific siRNAs targeting EPHB4." (PMID 31641103, 2019). "Upon heterotypic collisions between prostate cancer cells and fibroblasts, the CIL response was dramatically decreased owing to enriched levels of EphB3 and EphB4 in the prostate cancer cells." (PMID 30154457, 2018). "In silico analysis of a prostate cancer progression microarray publically available in the Oncomine database showed that both EPHB4 and ITGB8 are highly expressed in prostatic intraepithelial neoplasia, the precursor to prostate cancer." (PMID 25886373, 2015). "We also tested the PC3 prostate cancer cell line, which has been reported to over-express EphB4 endogenously and for which knockdown experiments have shown EphB4 expression is required for cancer cell viability, migration and invasion." (PMID 25831049, 2015). "This also identifies a new mechanism for EphB4 function in prostate cancer through the regulation of ITGB8, which our results show can contribute to prostate cancer cell motility." (PMID 25886373, 2015). "We have recently shown that EphB4 over-expression leads to a more aggressive phenotype in prostate cancer cells." (PMID 25886373, 2015). "To date, no study has investigated the broader consequences on gene expression of siRNA-mediated knockdown of EPHB4 in prostate cancer." (PMID 25886373, 2015). "In the current study, validation experiments confirmed that ITGB8 was significantly down-regulated when EPHB4 was knocked down and moreover, was also up-regulated when EPHB4 was over-expressed in prostate cancer cells." (PMID 25886373, 2015). "Together, these results highlight that integrin β8 plays an important role in prostate cancer cell migration and invasion in both endogenous and exogenously over-expressing EphB4 cell models." (PMID 25886373, 2015). "In this study we set out to investigate the gene expression changes that occurred when EPHB4 was knocked down in LNCaP prostate cancer cells that are endogenously over-expressing EphB4." (PMID 25886373, 2015). "Through gene expression analysis following EPHB4 knockdown, validation of the microarray data, and EphB4 over-expression, we have determined that EphB4 regulates the expression of integrin β8 in prostate cancer cell lines." (PMID 25886373, 2015). "EphB4 is expressed in prostate cancer cell lines with increased expression in human prostate cancers when compared with matched normal tissue." (PMID 16171530, 2005). "Immunohistochemistry was also used to examine localisation of EphB4 in tissue samples from 15 patients with prostate carcinomas." (PMID 16171530, 2005). "The relative expression of EphB4 in three prostate cancer cell lines was determined using reverse transcription and real time PCR using two different real-time PCR machines." (PMID 16171530, 2005). "Further investigation is needed to determine the roles of EphB4 in prostate cancer development and progression." (PMID 16171530, 2005).
prostate carcinoma (continued). "Using immunohistochemical techniques, we showed that EphB4 is produced in increased amounts in human prostate cancer tissue compared with adjacent normal tissue and that this immunoreactivity was associated with the tumour epithelial cells themselves." (PMID 16171530, 2005). "RT-PCR, western blotting and immunohistochemical techniques were used to examine EphB4 expression and protein levels in human prostate cancer cell lines LNCaP, DU145 and PC3." (PMID 16171530, 2005). "EphB4 immunoreactivity in vivo was significantly greater in human prostate cancers as compared with matched normal prostate epithelium and there appeared to be a trend towards increased expression with higher grade disease." (PMID 16171530, 2005). "Foci of prostate cancer within these samples showed brown staining indicating immunoreactivity to the EphB4 antibody and therefore the presence of the EphB4 protein." (PMID 16171530, 2005). "Thus EphB4-ephrin-B2 pathway has sustained role from initiation to progression in prostate cancer including androgen independence." (PMID 40044981, 2025). "Secondly, we hypothesized that EphB4 remains relevant when prostate cancer becomes androgen independent." (PMID 40044981, 2025). "EphB4 protein levels have previously been reported in prostate cancer tissue." (PMID 40044981, 2025). "Additionally, an ELISA was performed to measure EphB4 phosphorylation in PC3 prostate cancer cells and EphB4 stably expressing HEK293 cells following treatment with commercially available ephrinB2-Fc (ephrinB2-Fc R&D), ephrinB2-Fc-His, and Fc-TNYL-RAW-GS." (PMID 39489818, 2025). "However, EphA5 and EphB4 are present at both the plasma membrane and the cytoplasm of lung cancer and prostate cancer cells, respectively." (PMID 36214254, 2022). "It has also been shown that EphB4 regulates the expression of the integrin β8 receptor and that this might be promoting prostate cancer cell motility." (PMID 33430066, 2021). "Collectively, these results indicate that EPHB4 is a valuable prognostic biomarker and raises the hypothesis that it could be a therapeutic target in prostate cancer patients." (PMID 31641103, 2019). "In this study, we show that targeting the receptor tyrosine kinase EPHB4 could sensitize prostate cancer to immune checkpoint blockade therapy." (PMID 31641103, 2019). "Furthermore, overexpression of EphB4 has been found in several tumor types including ovarian and prostate cancer, among others." (PMID 29207612, 2017). "Otherwise, EPHB4 has been detected in the nucleus of prostate cancer cells and other authors assure that presence of receptor tyrosine kinases in this cell compartment is possible through several mechanisms including receptor internalization upon ligand binding and enzymatic cleavage." (PMID 26870995, 2016). "Therefore, we sought to determine the genome-wide changes upon transient knockdown of EPHB4 in a ligand-independent context in the prostate cancer cell line LNCaP." (PMID 25886373, 2015). "It would be interesting to investigate whether the transcription factors of the SP family can also influence EPHB4 expression in prostate cancer and thus be responsible for co-regulating ITGB8 and EPHB4." (PMID 25886373, 2015). "Targeting the αvβ8 integrin in combination with EphB4 targeted therapies may represent a future avenue for prostate cancer therapy." (PMID 25886373, 2015). "Prostate cancer also has induction of EphB4 which provides growth and survival advantage." (PMID 25148033, 2014). "Although the exact function of EphB2 in normal urothelium is unknown, this reciprocal expression of EphB2 and EphB4 is reminiscent to what has been observed in colon and prostate cancer." (PMID 25148033, 2014). "We hypothesize that upregulation of EphB4 expression in metastatic prostate cancer cells could enhance their invasion through deregulation of contact inhibition." (PMID 23495724, 2013). "All three prostate cancer cell lines expressed the EphB4 gene and protein." (PMID 16171530, 2005).
prostate carcinoma (continued). "PI3K pathway activation is a common and early event in prostate cancer, from loss of function mutations in PTEN, or activating mutations in PIK3Ca or AKT leading to constitutive activation, induction of growth factor-receptors kinase EphB4 and its ligand ephrin-B2." (PMID 40044981, 2025). "Indeed, the IGFIR had been also shown to upregulate EphB4 in prostate cancer but under the conditions used, such effect could be linked to both transcriptional and post-transcriptional mechanisms such as the presence of Ins receptor/IGFIR hybrids." (PMID 31270394, 2019). "However, neither the underlying mechanisms nor the functional consequences of EPHB4 inhibition in advanced prostate cancer are well understood." (PMID 31641103, 2019). "Targeting both EphB4 and integrin β8 may provide new options for treating prostate cancer." (PMID 25886373, 2015). "EphB4 may therefore be a useful anti-prostate cancer target." (PMID 16171530, 2005). "EphB4 and ephrin-B2 receptor ligand pair is induced in PTEN null prostate cancer, which significantly contributes to the tumor initiation." (PMID 40044981, 2025). "Thus, targeting EPHB4 could represent a viable modality for treating advanced prostate cancer." (PMID 31641103, 2019). "Our data demonstrated that EPHB4 inhibition decreased the level of SRC and also positively correlated with SRC kinase in prostate cancer patients." (PMID 31641103, 2019). "The high level of expression of both EPHB4 and ITGB8 in clinical PIN samples suggests that their increased expression is an early event in the development of prostate cancer." (PMID 25886373, 2015). "Over-expression studies have confirmed this, showing that increasing EphB4 levels can confer a transformed phenotype (breast MCF10A) and an increased metastatic phenotype (prostate cancer 22Rv1)." (PMID 25831049, 2015). "The trend of increasing EphB4 reactivity toward higher grade disease seen in this pilot study might suggest that it is more important in the later stages of the tumour development such as metastasis and further investigation of EphB4 in the development of prostate cancer is warranted." (PMID 16171530, 2005). "EphB4 knockdown lowered EphB4 and the PI3K downstream markers pAKT (Thr308) and phosphorylated ribosomal protein S6 (pS6, Ser235/Ser236) in PC3 and castrate-resistant prostate cancer cell lines C4-2B and 22Rv1." (PMID 40044981, 2025). "In vitro studies showed that TNYL-RAW-CCPM NPs selectively bound to EphB4-positive PC-3M prostate cancer cells but not to EphB4-negative A549 lung cancer cells." (PMID 37241862, 2023). "In addition, we have also checked the available human prostate cancer patient dataset for EPHB4 correlation with SRC and found that EPHB4 was positively correlated with SRC kinase in prostate cancer patients." (PMID 31641103, 2019). "Together, these data suggest that EPHB4 and ITGB8 are co-regulated in prostate cancer cells." (PMID 25886373, 2015). "This could indicate that EPHB4, ITGB8 and TGFB1 are intrinsically regulated in prostate cancer cells, therefore contributing to cancer progression and metastasis through the process of EMT." (PMID 25886373, 2015). "Comparison of the combined data for each cell line showed that there was no statistical difference in the level of EphB4 expression in the three prostate cancer cell lines." (PMID 16171530, 2005). "Since c-Myc and PI3K regulate AR levels, while AR regulation was not the focus of this study, it remains to be studied how EphB4 may regulate AR in prostate cancer." (PMID 40044981, 2025). "In an effort to characterize the contribution of EphB4 to regulating gene expression in prostate cancer, endogenously EphB4-expressing LNCaP cells were transfected with EPHB4 specific siRNAs and compared to negative non-silencing siRNA cells using gene expression profiling." (PMID 25886373, 2015).
prostate carcinoma (continued). "Forced over-expression of EphB4 in non-tumorigenic MCF10A breast cells and in 22Rv1 prostate cancer cells led to transformation of the MCF10A line and increased the metastatic phenotype of the 22Rv1 cells." (PMID 25831049, 2015).
colorectal cancer (19 papers, 2008 to 2025). A primary or metastatic malignant neoplasm that affects the colon or rectum. "In colorectal cancer patients, low tumor EPHB4 levels are associated with poor prognosis." (PMID 27314328, 2016). "Indeed, in colorectal cancer, while increased EphB4 expression is associated with longer patient survival, inhibition of EphB4 leads to decreased cell proliferation and metastasis and expression of EphB4 enhances tumor growth." (PMID 23844053, 2013). "Ephrin type-B receptor 4 (EPHB4), which belongs to receptor tyrosine kinases (RTKs) expressed extensively in variety of tumours such as lung cancer, colorectal cancer, and malignant soft tissue sarcoma, including rhabdomyosarcoma (RMS)." (PMID 38803845, 2024). "Conversely, the expression of EphB4 is upregulated in colorectal cancer, suggesting that it functions as a tumour promoter." (PMID 33430066, 2021). "The overexpression of EPHB4 in colorectal cancer cells promotes its proliferation and migration, invasion, and angiogenesis." (PMID 34336153, 2021). "By overexpressing EphB4 in colorectal cancer cell lines using EphB4 expression vectors, vascularisation and migratory ability were enhanced." (PMID 33430066, 2021). "Overall, these results indicate that colorectal cancer is distinct from other cancer types in displaying higher expression of EphrinB2 and its receptors EphB1, EphB2, EphB3, and EphB4." (PMID 31545551, 2019). "We examined the expression of EphrinB2 ligand and the EphrinB2 signaling receptors (EphB1, EphB2, EphB3, EphB4, and EphA4) in colorectal carcinoma." (PMID 31545551, 2019). "To evaluate the effects of EphB2 depletion, we selected the SW620 colorectal carcinoma cell line, which contains abundant EphB2, whereas EphB1, EphB3, and EphB4 are undetectable and EphA4 is detected at low levels." (PMID 31545551, 2019). "We extended analysis of the effects of NVP and NVP‐Iso on cell proliferation to include the 10 colorectal carcinomas cell lines in which the silencing EphrinB2, EphB2, or EphB4 significantly reduced cell proliferation." (PMID 31545551, 2019). "The results show that NVP and NVP‐Iso were significantly less effective at reducing the proliferation of HT‐29 and SW620 colorectal carcinoma cells after EphB2 (sh424) and EphB4 (sh774) were both silenced compared to the control cells." (PMID 31545551, 2019). "In this study, EphA2 and EphB4 are evaluated as targets for IGOS of colorectal cancer by immunohistochemistry (IHC) using a tissue microarray (TMA) consisting of 168 pairs of tumor and normal tissue." (PMID 28165374, 2017). "In conclusion, both EphA2 and EphB4 show potential as target for image-guided colorectal cancer surgery, but EphB4 seems to have the best characteristics with respect to tumor/normal mucosa distribution, as shown in a relatively large cohort of 168 patients." (PMID 28165374, 2017). "Based on its more consistently higher score in colorectal tumor tissue compared to normal tissue, EphB4 appears to be a promising candidate for IGOS of colorectal cancer." (PMID 28165374, 2017). "We discuss predicted functions for the gene products of MLH1, PMS2 and EPHB4, all of which have an established importance for colorectal cancer." (PMID 21171995, 2010). "Since the EPHB receptors (EPHB2, EPHB3 and EPHB4) follow a similar pattern of transcriptional silencing in colorectal cancers, all EPHB receptor family members probably play a similar role in this disease." (PMID 18682749, 2008). "Moreover, upregulation of EphB4 in gastric cancer and colorectal cancer resulted in increased metastasis." (PMID 35163601, 2022). "In colorectal cancer, the expression of a dominant negative EphB4 was shown to facilitate growth." (PMID 35163601, 2022). "Thus, EphrinB2 and its receptors EphB2 and EphB4 are general regulators of colorectal carcinoma cell proliferation/viability." (PMID 31545551, 2019).